THY1 (Thy-1 cell surface antigen)
Diseases named in the same sentence as THY1 in open-access papers (continued):
Sharing a sentence is not in itself a finding about the gene and the disease.
tumor (continued). "To determine the presence of MSCs at the tumor site, we performed qRT-PCR to quantitate gene expression of the Thy-1 gene, which is specific to MSCs." (PMID 32295145, 2020). "Recently we showed that CD90 (THY1) expression controls tumor cell migration/adhesion mainly through SRC signaling." (PMID 31064137, 2019). "By using an immunodeficient Rag−/− mouse model, it has been shown that NKp46−CD4−ILC3 accumulation leads to IL-17 and IL-22 production, which promotes tumor development, whereas depletion of ILCs with anti-Thy1 mAbs limits tumor growth in colon cancer." (PMID 32117199, 2019). "THY1 was decreased at the first time point then it increased, as also observed in the progressing tumor." (PMID 29527515, 2018). "The effect of Thy-1 in cellular adhesion of leukocytes and tumor cells to endothelial cells has attracted the attention of researchers." (PMID 30389973, 2018). "We observed that Thy1 was expressed at increased levels in primary cultures obtained during cisplatin/pemetrexed adaptation and as well during tumor progression, although to a lower extent." (PMID 29527515, 2018). "Thy-1+ cells were present in band-like stromal structures (arrows) and at the invasive front on the tumor periphery (insets)." (PMID 28744021, 2017). "A very recent study performing high-throughput analysis of NMIBC revealed a Class 2 tumor that associates with progression, these Class 2 tumors enriched for cancer stem cell markers such as ALDH1A1, ALDH1A2, PROM1, NES and THY1." (PMID 27655672, 2016). "CD90 (Thy-1) was strongly expressed in all EWS samples.CD105 (endoglin) was positively expressed in tumor cells and strongly expressed in the cells surrounding the tumor vessels." (PMID 24498265, 2014). "Inoculation of T-lymphoblast cells with prepubertal primate testis cells still has a remainder of 0.1% of tumor cells after FACS sorting for CD90+(THY-1+) and CD45−, and the remaining tumor cells were able to form tumors after transplantation to nude mice." (PMID 23509797, 2013). "For characterization of stemness as a possible cause of tumor cell plasticity, the well established stemness markers Thy-1, Oct-4, Sox-2 and Nanog were analyzed, after total RNA extraction from tumor tissue." (PMID 23547746, 2013). "Especially, in the context of HCC tumor stem cell research, Thy-1 expression is discussed as one crucial regulator of stemness and its upregulation is described in the context of chemoresistance." (PMID 23547746, 2013). "The transition from Thy1+ to a Thy1− phenotype in nasopharyngeal mucosa is a feature of carcinogenesis, and thus suggests that Thy1 represents a candidate as a tumor suppressor." (PMID 22619682, 2012). "In low-grade WAP-T tumors we noted that Thy1 as well as Sca1 expression is mostly restricted to the stromal compartment and to adjacent tumor cells." (PMID 20730114, 2010). "Immunohistochemical staining showed the tumor cells were Thy1 positive and retained expression of human Bcl-2." (PMID 18382684, 2008). "Using oligonucleotide microarray analysis mapping close to a previously defined 11q22-23 NPC critical region, THY1 showed consistent downregulated expression in the tumour segregants." (PMID 17199893, 2007). "Similarly, in GC, high THY1 expression correlates with aggressive tumor behavior, increased metastatic potential, and worse patient outcomes." (PMID 40476057, 2025). "Addressing these questions is crucial for elucidating the role of THY1 in tumor progression." (PMID 40476057, 2025). "Moreover, THY1-positive GC tumor cells have been shown to resist conventional chemotherapy, reinforcing their roles in tumor progression and therapy resistance." (PMID 40476057, 2025). "Thy1 inhibition blocked the adhesion of tumor cells to mouse lymphatic endothelial cells." (PMID 40244063, 2025). "Additionally, THY1 itself has been described as a regulator of cell–matrix interactions, reinforcing its role in modulating the tumor microenvironment." (PMID 40476057, 2025).
tumor (continued). "Given the context-dependent nature of THY1 expression and its established association with the EMT and tumor progression, we hypothesized that THY1 is embedded within a transcriptional program that governs invasion and metastasis in GC." (PMID 40476057, 2025). "In this study, we first demonstrated that the NPC tumor suppressor THY1 could inhibit the activation of SRC." (PMID 37046850, 2023). "We had previously identified THY1 as a tumor suppressor in NPC." (PMID 37046850, 2023). "Thus, further studies are needed to address the contribution of THY1 expression in each of these populations to tumor biology." (PMID 38254918, 2023). "From these data, we cannot directly distinguish whether increased expression of the THY1 gene in the tumor is a consequence of its increased expression in tumor cells, in mesenchymal cells of the tumor microenvironment, or both." (PMID 38254918, 2023). "Furthermore, it was shown that IGC tumor cells with high expression of THY1 have a greater capacity for tumorigenesis and metastasis in vitro." (PMID 38254918, 2023). "In this study we show that tumor invasion could be suppressed by THY1 via adherens junction formation in a few NPC cell lines, and knockdown of THY1 would disrupt this cell-cell adhesion phenotype." (PMID 37046850, 2023). "In some studies on OC, THY-1 was suggested to have a tumor-suppressive role." (PMID 37628927, 2023). "In contrast, expression of C3, SFRP2, STAT3, IL-6 and THY1 was increased in tumor-distal stroma." (PMID 37350578, 2023). "The role of PDGF-Rβ in SRC activation and THY1-mediated suppression of tumor invasion was examined." (PMID 37046850, 2023). "Importantly, large tumor counts in DMBA+Ab mice were significantly lower compared to DMBA mice, suggesting limited tumor expansion in mice treated with the anti-Thy1 antibody." (PMID 36675138, 2023). "In addition, there were two other phenotypes namely A-SMA+/Thy-1+(closer to tumor cells in classic ILC) and FAP+/S-100+ (closer to tumor cells in pleomorphic ILC), which showed a trend of significance." (PMID 38192631, 2023). "In addition, F1 also specifically expressed THY1, indicating an activated fibroblast subset and playing an important role in tumor-supported collagen synthesis." (PMID 35265520, 2022). "Interestingly, Thy-1/CD90, one of the CD97 ECD binding partners, is considered a GBM stem cell marker, but it is also present in more differentiated GBM and many tumor-associated cells." (PMID 35563846, 2022). "Furthermore, in HCC, THY1 expression is related to poor tumor differentiation, invasive properties, and dismal prognosis." (PMID 35172861, 2022). "rWISP-1 inhibited the migration and invasion of CD326+ tumor cells and Thy1+ CAFs." (PMID 36241874, 2022). "Future applications of this mouse model may provide versatility for in vivo testing of neovasculature‐targeted UCAs in mice by simply replacing the human Thy1 gene by any other human gene relevant to tumor angiogenesis." (PMID 33532585, 2021). "Interestingly, flow cytometric analysis of dissociated tumor tissue revealed that almost all tumor cells in which FAP was detected also co‐expressed the CD90 (Thy‐1) surface antigen." (PMID 33082953, 2020). "Thus, the role of Thy-1 in cancer seems ambiguous, whereby tumor promoting or suppressing activities appear to depend on the cancer cell type and tumor microenvironment." (PMID 33511115, 2020). "We used our previously established syngenic orthotopic GBM model in immunocompetent C57BL/6 Thy1-CFP//LysM-EGFP//CD11c-EYFP triple-transgenic animals that recapitulates the typical features of the GBM tumor and is suitable for intravital two-photon imaging analyses." (PMID 31660979, 2019). "Additionally, in cancer associated fibroblasts, Thy-1/CD90 induces inflammation and increases tumor progression by promoting IL-6 secretion." (PMID 31428610, 2019).
tumor (continued). "Furthermore, there is evidence that high metastatic tumor ECs express higher Thy-1 mRNA levels compared with low metastatic tumor ECs suggesting heterogeneity of ECs in tumors." (PMID 24236063, 2013). "Prior analysis of these tumors using functional assays of tumor initiating potential have showed that the tumor-generating cells had a predominantly basal character, and they were enriched in a Thy1+/CD24+ cell sub-population (1% of total Lin− cells, showing 35× enrichment of functional activity)." (PMID 21541292, 2011). "Mice injected intramuscularly with either subset had enlarged spleens by the second week of tumour growth caused largely by the accumulation of Ig, Lyt-1 and Thy-1 negative cells." (PMID 3501729, 1987). "THY1 was reported to play pivotal roles in a variety of malignant diseases, and the functions of THY1 had tissue heterogeneity, which indicated that it could be an oncogene or a tumor suppressor gene at different diseases." (PMID 38819947, 2024). "We hypothesized that THY1 can suppress tumor invasion in NPC via inhibition of SRC." (PMID 37046850, 2023). "However, it is unknown whether, in tumors, CD97 indeed interacts with Thy-1 on the cells present there, such as the tumor cells themselves, (activated) endothelial cells, or fibroblasts." (PMID 35563846, 2022). "Binding of TAM surface ligands Thy1 and EphA4 with EphA4 receptor of breast CSCs activated Src and NF-κB pathways, which in turn reinforced the secretion IL-6, IL-8 and granulocyte–macrophage-colony stimulating factor (GM-CSF), providing the self-renewal of tumor cells in vitro." (PMID 36613838, 2022). "Furthermore, it can often yield a non-diagnostic, Thy1, result or a Thy3 cytology outcome, i.e. “neoplasm possible” neither definitively benign or malignant – creating further uncertainty." (PMID 33989038, 2021). "Furthermore, THY1 was associated with tumor metastasis, tumor category, and tumor stage in LUAD, which implies that THY1 has an immunosuppressive role in TME and might be responsible for immunotherapy resistance." (PMID 35071018, 2021). "The PA showed alterations in CDK18 and THY1 mRNA isoforms which could be tumor specific." (PMID 33261069, 2020). "Noteworthy, in WAP-T tumors Thy1-expressing cells are mostly located within or close to fibroblastic stroma, which likely originates from recruited normal mesenchymal stem cells and probably provides a seeding niche for tumor cells undergoing mesenchymal differentiation." (PMID 20730114, 2010). "VARGG accurately reveals the spatial organization of tumors and identifies key genes related to tumor progression and immune microenvironment (VEGFA, CD74, SPP1, IGFBP5, TIMP2, EMP1, THY1)." (PMID 41275376, 2025). "To further assess early tumour–axon interactions, we next measured YFP fluorescence in individual WM bundles of the tumour-involved striatum in npp Thy1-YFP tumours at the intermediate stage and correlated it to tumour density." (PMID 40836081, 2025). "Top hits include changes in transcriptional regulation (ZNF385B, SNORA65), tumour microenvironment (COL1A2, COL3A1), and metastatic processes (UCHL1, SUCNR1, THY1)." (PMID 40890143, 2025). "PD-L1, PD-L2, THY1, and SPP1 from tumor or immune-inhibited cells play a central role in inhibiting the function of CD8_Tpex and CD8_Tex cells during anti-tumor immunity." (PMID 38886748, 2024). "It provides us with a new therapeutic strategy for LUSC by blocking THY1 to remolding ECM and tumor microenvironment." (PMID 38819947, 2024). "Our comprehensive specialized CAF multiplex panel which used protein-based detection consisted of most commonly used markers for CAF: Alpha-SMA, FAP, S100 and Thy-1 with CD45 and Pan CK to identify hematopoietic cells and tumor cells respectively." (PMID 38192631, 2023). "Gene expression of COL1A1, COL1A2, COL6A3, FN1, and THY1 in CAFs as well as COL4A1 and COL4A2 in Angiogenic_EC had a highly significantly positive correlation with the proportion of malignant tumor cells." (PMID 38002057, 2023).
tumor (continued). "KIT, CD34, THY1, and EPCAM were expressed in large vessel structures and tumor capsules from patients #4001 and #3559." (PMID 37932266, 2023). "To confirm THY-1 protein transfer, we incubated blood-derived monocytes with patient-matched HCC tumor tissue fragments for 6 days and found that monocytes indeed acquired THY-1 protein from the TME." (PMID 37388918, 2023). "Previously we have found THY1, a cell surface glycoprotein, inhibits the invasion of NPC cells and functions as a tumor suppressor in NPC." (PMID 37046850, 2023). "Seven days after adoptive transfer, gene-of-interest (thy1.1) and control (GFP) transduced T cells in tumors, tumor draining lymph nodes, and spleens were quantified by flow cytometry." (PMID 38143765, 2023). "The high purity of the fibroblast and tumor cell populations was confirmed by selective expression of cell type-specific genes including CDH1, EPCAM, and KRT8 for tumor cells and VIM, DCN, THY1, and COL3A1 for fibroblasts." (PMID 36868311, 2023). "In tumour samples, the intercellular interactions were mainly active in signalling pathways, including pathways involving SPP1, VTN, NOTCH, THY1, and CD46." (PMID 36860314, 2023). "Pericytes play a crucial role in tumor neovascularization; consistently, we observed a strong angiogenic signature (such as for ANGPT2, CAV1, PDGFA, THY1, EGFL6, and GMFG) in pericytes." (PMID 37853464, 2023). "rWISP-1 also blocked signaling pathway activation and the protein expression of MMP2 and MMP12 in CD326+ tumor cells and reduced the mRNA expression levels of CAF activation markers in Thy1+ CAFs." (PMID 36241874, 2022). "Thy-1 is a cancer stem cell marker and, like CD97, regulates tumor migration, invasion, and metastasis." (PMID 35563846, 2022). "LA supported an upregulation of Podoplanin (Pdpn) and Thy1 and downregulation of IL7 in FRCs of TDLNs, making them akin to activated fibroblasts found at the primary tumor site." (PMID 35362044, 2022). "In agreement, based on three different algorithms, we observed a positive correlation between THY1/CD90 gene expression and a CAF gene signature across TCGA MPM tumor samples." (PMID 34987640, 2022). "To test differences in the concentration of each biomarker between the tumor tissue and the surrounding area, we plotted the median distribution differences (and their interquartile ranges) of NOTCH1, HES1, and THY1 in those areas in the whole population." (PMID 35172861, 2022). "In dermal fibroblasts, Thy-1/CD90 surface protein engages β3 integrin in trans on adjacent cells, including fibroblasts or tumor cells." (PMID 31428610, 2019). "How is Thy-1/CD90 able to perform “hero and villain” functions and act as tumor suppressor or tumor promoter, respectively, using the same molecular signaling pathways?" (PMID 31428610, 2019). "Thus, the negative correlation of TWIST1 (r = -0.54, p < 0.01), LAMB1 (r = -0.58, p < 0.001), and THY1 (r = -0.48, p < 0.01) in low tumor Hp expression groups could be a signature of poor cancer differentiation also the prognostic role of Hp in HCC cancer cell differentiation." (PMID 28158312, 2017). "Cells that co-express Thy-1 and α-smooth muscle actin (αSMA), a CAF marker, were located on the tumor periphery surrounding collectively invading tumor cells and in perivascular regions." (PMID 28744021, 2017). "Analysis of leukocyte tumor content by flow cytometry indicated that anti-PD-1 injection in WT mice induced a small, yet significant, increase in CD45+ and Thy1+ T cells, including both CD8+ and, albeit to a lesser extent, CD4+ TILs." (PMID 29273790, 2017). "The tumor origin of Thy1-expressing cells was further confirmed by co-staining with the SV40-LT specific antibody, which we used to distinguish between tumor cells and cells provided by recipient mice." (PMID 20730114, 2010).
tumor (continued). "Expression of stromal cell genes PENK and THY1/CD90 was minimal indicating that CD26 sorting was efficient enough to exclude CD90+ stromal cells, the other major cell type of tumor tissue." (PMID 20021671, 2009). "Searches for putative TSGs have identified only few candidates, with tumor-specific promoter methylation, such as BLU and RASSF1A at 3p21, CADM1/TSLC1 at 11q23.1; THY1/CD90 at 11q22.3, CDH1 at 16q22.1, RASAL1, ADAMTS18 and CDH13 at 16q23." (PMID 18714356, 2008). "BIRC5 showed affinity for anti-mitotic agents such as berberine, aligning with its function in cellular survival, whereas THY1 and FN1 were anticipated to engage with immune checkpoint inhibitors, reinforcing their promise in combinatorial therapy designed to augment anti-tumour immunity." (PMID 40475773, 2025). "THY1 enhances CAF activity, leading to an immunosuppressive environment, while PDGFRA fosters fibrosis, further hindering immune cell access to the tumor." (PMID 40817072, 2025). "In particular, GGACT, LXN, THY1, SYNPO2, ACMSD and COLEC11 showed no survival or recurrence associations from the tumor data, suggesting these as unique biomarkers from NAT." (PMID 37575948, 2023). "Nonetheless, the molecular mechanisms underlying the tumor cell behavior and poor prognosis observed in patients with IGC tumors expressing high levels of THY1 have not yet been clarified, with few studies addressing this issue." (PMID 38254918, 2023). "THY1 is not a canonical fibroblast marker but is typically expressed on subsets of myofibroblasts and here we also observed increased levels in the tumor-distal region." (PMID 37350578, 2023). "Tumor macrophages did not express THY-1 mRNA but acquired the protein from the HCC tumor microenvironment." (PMID 37388918, 2023). "Finally, immunochemistry analysis showed hydrogen peroxide /p38/Nrf2 stress strongly inhibited the production of tumor markers CD133, Thy1, and napsin, which correlate with migration and invasion in cancer cells." (PMID 36672696, 2023). "Our study demonstrated that THY1 could inhibit the activity of SRC, and that can resulted in the maintenance of adherens junctions and suppression of tumor metastasis in NPC for the first time." (PMID 37046850, 2023). "The anti-Thy1 antibody reduced tumor burden and limited tumor expansion in DMBA+Ab mice and did not have any effect on ILCs." (PMID 36675138, 2023). "We observed that, after anti-Thy1 antibody treatment in the DMBA+Ab group, the number of large tumors, tumor incidence, and lymphocyte infiltration were significantly reduced compared to the DMBA group, indicating that inhibiting ILCs limited tumor expansion and tumor burden." (PMID 36675138, 2023). "Notably, injection of ApoSQ changed Thy1+ CAF and CD326+ tumor cell phenotypes, attenuating their migratory and invasive activities and inactivating related signaling pathways." (PMID 36241874, 2022). "Moreover, immunohistochemical analysis of serial sections of primary tumor tissue showed that LY3039478 reversed the reduction in α-SMA expression and increases in NICD1 and WISP-1 expression in Thy1+ CAFs." (PMID 36241874, 2022). "Pericyte-1 was enriched in the tumor fraction and characterized by higher expression of genes related to a pro-inflammatory capillary phenotype (RGS5, KCNJ8, AXL, ABCC9, PDGFRB, and THY1)." (PMID 36180422, 2022). "Among the top enriched signaling pathway network, the interactions between THBS2+ CAFs and other cells within the tumor micro-ecosystem were most mediated by THBS, followed by stromal/immune signaling pathways, e.g. THY-1, FN-1, TGF-β, IL6/4, MHC-I, VEGF, CD40, or TIGIT." (PMID 35547750, 2022). "Additionally, immunofluorescence analysis of primary tumor tissue and isolated Thy1+ CAFs confirmed the reduced α-SMA expression and increased NICD1 and WISP-1 expression in Thy1+ CAFs after injection of ApoSQ." (PMID 36241874, 2022).